LINC01556 (long independently transcribed non-coding RNA 1556)
Synonyms: dJ25J6.5; formerly C6orf100
Gene: Long non-coding RNA gene on chromosome 6 (28,922,706 to 28,944,717, forward strand). Ensembl gene ENSG00000204709.
Gene Ontology:
Molecular function: triplet codon-amino acid adaptor activity
Biological process: translation
Diseases named in the same sentence as LINC01556 in open-access papers:
LINC01556 is named in the same sentence as 1 disease in open-access papers, as found by Europe PMC text mining. Sharing a sentence is not in itself a finding about the gene and the disease.
LINC01556 shares sentences with these, for which no sentence is quoted: Sepsis (1 paper).